EPS8L2 (EPS8 signaling adaptor L2)
Description:
Stimulates guanine exchange activity of SOS1. May play a role in membrane ruffling and remodeling of the actin cytoskeleton. In the cochlea, is required for stereocilia maintenance in adult hair cells (By similarity).
Synonyms: EPS8R2; FLJ21935; FLJ22171; MGC3088; DFNB106
Tractability: Antibody: its Gene Ontology location is reachable by antibodies, with medium confidence. PROTAC: ubiquitination databases record sites on it; its protein half-life has been measured.
Gene: Protein-coding gene on chromosome 11 (694,438 to 727,729, forward strand). Ensembl gene ENSG00000177106.
Subcellular location: Cytoplasm; Cell projection, stereocilium
Subcellular location (Human Protein Atlas): Centrosome; Cytosol
Pathways (Reactome):
Sensory Perception: Sensory processing of sound by inner hair cells of the cochlea; Sensory processing of sound by outer hair cells of the cochlea
Gene Ontology:
Molecular function: actin binding; cadherin binding; guanyl-nucleotide exchange factor activity; protein binding
Biological process: positive regulation of ruffle assembly; regulation of Rho protein signal transduction; Rho protein signal transduction; sensory perception of sound
Cellular component: cytoplasm; cytosol; extracellular exosome; protein-containing complex; ruffle membrane; vesicle; plasma membrane; stereocilium bundle; stereocilium tip; stereocilium
Genetic constraint (gnomAD): Loss-of-function variants: 75 observed, 78.05 expected, observed/expected ratio (o/e) 0.96, 90% interval 0.8 to 1.16. The synonymous counts are far from expectation, so gnomAD's model fits this gene poorly and the ratio says little. Missense variants: 1,096 observed, 831.26 expected, observed/expected ratio (o/e) 1.32, 90% interval 1.25 to 1.39. Synonymous variants: 482 observed, 352.05 expected, observed/expected ratio (o/e) 1.37, 90% interval 1.27 to 1.48.
Gene-disease validity (ClinGen):
ClinGen rates the evidence that EPS8L2 causes each of these diseases.
nonsyndromic genetic hearing loss (autosomal recessive): Moderate. A disease characterized by hearing loss that is not part of a larger syndrome.
Homologues: Orthologues: macaque EPS8L2 (94% identical), pig EPS8L2 (86% identical), mouse Eps8l2 (86% identical), guinea pig EPS8L2 (86% identical), dog EPS8L2 (85% identical), rat Eps8l2 (85% identical), chimpanzee EPS8L2 (80% identical), tropical clawed frog eps8l2 (59% identical), zebrafish eps8l2 (56% identical), Caenorhabditis elegans eps-8 (29% identical), Drosophila melanogaster CG8907 (26% identical), Drosophila melanogaster aru (25% identical), and 1 more. Paralogues in human: EPS8 (45% identical), EPS8L1 (40% identical), EPS8L3 (25% identical).
Diseases named in the same sentence as EPS8L2 in open-access papers:
EPS8L2 is named in the same sentence as 17 diseases in open-access papers, as found by Europe PMC text mining. Sharing a sentence is not in itself a finding about the gene and the disease. The quoted sentences say what the papers report.
deafness (5 papers, 2015 to 2023). An inherited or acquired condition characterized by the complete loss of the ability to hear from one or both ears. "These cells expressed several causal genes for various deafness forms, including Eps8l2, Gjb2, Gjb6, Homer2, Coch, Clic5, Dcdc2a, Pou3f4, Col4a6, and Six1." (PMID 37339214, 2023). "A frame-shift variant (c.1014delC; p.Ser339Alafs*15) was identified in EPS8L2, encoding Epidermal growth factor receptor Pathway Substrate 8 L2, a protein of hair cells’ stereocilia previously implicated in progressive deafness in the mouse." (PMID 26282398, 2015). "The other 6 variants were associated with recessive forms of deafness (TMPRSS3, GPSM2, BDP1, EPS8, EPS8L2, and PCDH15)." (PMID 33809266, 2021).
hearing loss (4 papers, 2015 to 2026). "This study serves as a valuable expansion to the mutational landscape of EPS8L2-associated hearing loss." (PMID 41514136, 2026). "This study expands the mutational and clinical spectrum of EPS8L2-associated hearing impairment by identifying five additional individuals in four families, more than doubling the number of reported cases to date, while going deeper into clinical aspects." (PMID 41514136, 2026). "In humans, EPS8L2-associated hearing loss has so far shown a prelingual onset with high frequencies most severely affected." (PMID 41514136, 2026). "We present five affected individuals from four families with EPS8L2-associated hearing impairment with clinical information, substantially contributing to the limited number of cases and alleles currently reported." (PMID 41514136, 2026). "To date, only 2 cases of EPS8L2-associated hearing loss caused by homozygous pathogenic variants have been reported in a single family." (PMID 41578500, 2026). "In summary, this work doubles the number of reported families with EPS8L2-associated hearing impairment." (PMID 41514136, 2026). "The progressive hearing loss identified in the EPS8L2 knockout mice phenocopied childhood hearing loss in humans and EOAD observed in Rhodesian Ridgebacks, indicating that this gene is required for the maintenance of the mature hair cells in the inner ear." (PMID 35385474, 2022). "Pathogenic variants in the EPS8L2 gene are known to underlie nonsyndromic progressive hearing loss." (PMID 41578500, 2026). "Among 33 protein coding genes in the EOAD-associated region based on the Ensembl gene annotation, EPS8L2 (Ensembl gene ID: ENSCAFG00000025183) was of particular interest because this gene was identified as a putative causal gene for hearing loss in consanguineous families in humans." (PMID 35385474, 2022). "EPS8L2 (DFNB106, OMIM 614988) has been identified as an autosomal recessive non-syndromic hearing loss-associated gene in humans as well, mirroring the progressive hearing loss in mouse models." (PMID 41514136, 2026). "We also show a unique U-shaped audiogram, which has not been previously reported for EPS8L2-associated hearing impairment in two individuals with the spliceogenic c.767C > G, p.(Thr256Arg) variant with a molecular effect r.701_768del, p.(Gly234Alafs*55)." (PMID 41514136, 2026).
bladder cancer (2 papers, 2019 to 2022). "Accumulating studies suggested that EPS8L2 is an exosome-secreted protein and could be used as a potential diagnostic biomarker for bladder cancer." (PMID 35820925, 2022).
lymph node metastasis (2 papers, 2025 to 2026). "Our analysis of multiomic features associated with lymph node metastasis led to the identification of a phosphopeptide belonging to the EPS8L2 protein." (PMID 41526910, 2026). "Clinical correlation analysis revealed that elevated EPS8L2 expression is associated with advanced tumor grade, lymph node metastasis, and unfavorable patient prognosis, suggesting its potential role in CRC progression and aggressiveness." (PMID 40783393, 2025). "We found that elevated EPS8L2 expression was significantly associated with tumor grade, lymph node metastasis, and CRC patients’ poor prognosis." (PMID 40783393, 2025).
autosomal recessive hearing loss 106 (1 paper, 2026). "Herein, we describe the first case of nonsyndromic autosomal recessive hearing loss 106 (DFNB106) harboring compound heterozygous pathogenic variants in EPS8L2." (PMID 41578500, 2026).
colorectal cancer (1 paper, 2025). A primary or metastatic malignant neoplasm that affects the colon or rectum. "Collectively, our findings position EPS8L2 as both a potential diagnostic biomarker and a novel therapeutic target for colorectal cancer intervention." (PMID 40783393, 2025). "In conclusion, our study establishes EPS8L2 as a critical oncogenic driver in colorectal cancer progression and metastasis." (PMID 40783393, 2025). "To further investigate whether Eps8l2 is involved in tumorigenesis, we generated Eps8l2 knockout mice (Eps8l2−/−) and wild-type littermates (Eps8l2+/+) to induce colorectal cancer." (PMID 40783393, 2025). "Furthermore, utilizing patient-derived colorectal cancer organoids as a clinically relevant model system, we demonstrated that EPS8L2 overexpression markedly enhanced organoid formation efficiency, reinforcing its functional role in promoting tumorigenic capacity." (PMID 40783393, 2025).
colorectal tumors (1 paper, 2025). "In addition, the number of colorectal tumors in Eps8l2−/− mice was significantly reduced compared with that in Eps8l2+/+ mice." (PMID 40783393, 2025).
cancer (9 papers, 2014 to 2025). A tumor composed of atypical neoplastic, often pleomorphic cells that invade other tissues. "In cancer, EPS8L2 was reported to be associated with testicular germ cell tumors’ drug resistance." (PMID 40783393, 2025). "PMM2, a glycosylation enzyme, could influence immune cell function, while EPS8L2 has been linked to neurotoxicity in cancer therapeutics." (PMID 40170606, 2025). "EPS8L2 was found to interact with Ctdnep1 to cause nuclear mispositioning by regulating dorsal actin cables for nuclear movement during cell migration, which is usually associated with cell dysfunction and disease, from muscular disorders to cancer metastasis." (PMID 36918772, 2023). "Interestingly, most of these genes are linked with cancer processes (Pld1, Fam13c, Svbp, TMem192, Zc3h7a, RTP4, Naa30, Zgrf1, Slc33a1, Dnmt3b, Map6, Plin4, Eps8L2, Alg12, Capg and Tdp2)." (PMID 37700325, 2023). "Genes containing AS events associated with overall survival are known components of cancer-related pathways, including regulation of transcription (E2F4, ZNF730, GPBP1, POLR2J, SP2, and CIART), cell cycle (E2F4 and GTSE1), or cell-cell adhesion (CEACAM1, MMP14, EPS8L2, AP3D1, AFDN, and PAK4)." (PMID 35044822, 2022). "Differentially methylated CpGs related to NXPH4 and LBX2 have previously been described in a study that developed a placental epigenetic clock, whereas aberrant methylation and/or expression of NXPH4, EPS8L2, AMOTL1, IRX2, and LBX2 have also been described in multiple types of cancers." (PMID 40338255, 2025). "Moreover, knockdown of G3BP2 effectively suppressed EPS8L2-mediated tumor growth in vivo, suggesting that G3BP2 is a critical downstream effector of EPS8L2 in cancer progression." (PMID 40783393, 2025). "Its precise role in cancer initiation or progression in mice has not been elucidated, largely because it shares redundant biological functions with other family members, namely Eps8L1, Eps8L2 and Eps8L3." (PMID 25359883, 2014).
tumor (3 papers, 2023 to 2025). "In vivo experiments showed that G3BP2 knockdown could impede increased tumor growth and tumor weight caused by EPS8L2 overexpression." (PMID 40783393, 2025). "The results showed that EPS8L2 knockdown significantly decreased tumor volume and weight in nude mice." (PMID 40783393, 2025). "Conversely, knockout of Eps8l2 markedly attenuated tumor development in an AOM/DSS-induced CRC mouse model." (PMID 40783393, 2025). "In this study, we identified EPS8L2 as a significantly upregulated gene in CRC tumor tissues, where it exhibits oncogenic properties." (PMID 40783393, 2025). "We then obtained a human CRC tissue microarray (TMA) and verified that EPS8L2 was highly expressed in tumor tissues compared with paired peri-tumor tissues." (PMID 40783393, 2025). "Two variants were identified in all tumor samples situated outside the lung and three lung samples (GPAM and EPS8L2)." (PMID 36968225, 2023). "The upregulation of EPS8L2 in tumor tissues was validated by RT-qPCR, western blotting, and IHC." (PMID 40783393, 2025). "Therefore, it will be worthwhile to explore the relationship of EPS8L2 with the tumor microenvironment and tumor immunity." (PMID 40783393, 2025). "Furthermore, Eps8l2 knockout led to decreased tumor incidence in an AOM/DSS-induced carcinogenesis model." (PMID 40783393, 2025). "EPS8L2 may enhance tumor growth by influencing stromal crosstalk and angiogenesis, or reshaping the immune microenvironment in vivo." (PMID 40783393, 2025). "The results indicated that EPS8L2 overexpression increased tumor volume and weight." (PMID 40783393, 2025). "Importantly, genetic ablation of Eps8l2 significantly attenuated tumor development in the AOM/DSS-induced CRC model." (PMID 40783393, 2025). "Moreover, tumor size was also decreased after Eps8l2 knockout." (PMID 40783393, 2025). "Of note, seventeen of thirty-nine proteins are reported as urine biomarkers in different diseases, of which eight proteins (PEBP1, EPS8L2, SERPINA1, FGA, SPINT1, CD55, SPARC, and GINM1) are related to neoplastic disease in urine specimens." (PMID 36918772, 2023). "To determine whether the Eps8l2-G3bp2 axis contributes to tumor development in this AOM/DSS model, we examined G3bp2 and Ki67 expression by IHC staining and found a significant decrease of G3bp2 and Ki67 expression levels in tumor tissues from Eps8l2−/− mice." (PMID 40783393, 2025).
EPS8L2 also shares sentences with these, for which no sentence is quoted: breast carcinoma (1 paper); colon cancer (1); endometrial cancer (1); endothelial dysfunction (1); Hearing impairment (1); muscular disorders (1); non‐small cell lung cancer (1); prostate carcinoma (1).